AQP1 (aquaporin 1 (Colton blood group))
Diseases named in the same sentence as AQP1 in open-access papers (continued):
Sharing a sentence is not in itself a finding about the gene and the disease.
atherosclerosis (6 papers, 2015 to 2025). A disease characterized by the build-up of fatty material and calcium deposition in the arterial wall resulting in partial or complete occlusion of the arterial lumen. "We have previously shown that loss of AQP1 accelerates angiotensin II-induced atherosclerosis in hyperlipidemic mice." (PMID 35203568, 2022). "Given that the accumulation of senescent ECs underpins the pathogenesis of atherosclerosis and atherosclerotic cardiovascular diseases, AQP1's significance extends beyond its impact on osmotic water permeability in the regulation of EC biology in aging." (PMID 39180980, 2024). "Here, we examined the role of KLF2 in regulation of AQP1 expression and studied expression of AQP1 mRNA and protein during the pathogenesis of atherosclerosis in human vascular tissue." (PMID 26717516, 2015). "Our data provide support for a continuous role of KLF2 in stabilizing the vessel wall via co-temporal expression of eNOS and AQP1 both preceding and during the pathogenesis of atherosclerosis." (PMID 26717516, 2015). "Moreover, genetic or pharmacological AQP1 disruption can be potentially suggested as a potential anti-senescence strategy for improvement of atherosclerosis during aging." (PMID 39180980, 2024). "In silico analysis of gene expression profiles from studies that assessed the effects of KLF2 overexpression in vitro and atherosclerosis in vivo on endothelial cells, identifies AQP1 as KLF2 downstream gene with elevated expression in the plaque-free vessel wall." (PMID 26717516, 2015). "Using immunohistochemistry, we subsequently verified whether the atherosclerosis stage-related differences in AQP1 mRNA levels correspond with differential expression of the AQP1 protein." (PMID 26717516, 2015). "In addition, AQP1 is expressed in human atherosclerotic angiopathy, and the lack of AQP1 enhances the formation of atherosclerosis in mice." (PMID 38335213, 2024).
bladder cancer (6 papers, 2021 to 2026). "MiR-3194-3p suppresses cell proliferation, migration, and invasion as well as promotes cell apoptosis in bladder cancer by targeting Aquaporin 1 (AQP1)." (PMID 34516362, 2021). "In particular, AQP1 plays a significant role in the pathogenesis of bladder cancer and may serve as a potential target for novel drug development." (PMID 42101308, 2026). "The expression of AQP1 and AQP3 in bladder cancer tissue was measured by immunohistochemistry and RT-PCR." (PMID 36532729, 2022). "The results showed that Polyporus could significantly downregulate the relative expression of AQP1 and AQP3 mRNA in bladder cancer tissue of rats, indicating that the anti-bladder cancer effect may be produced by regulating AQP1 and AQP3 in bladder cancer tissue." (PMID 36532729, 2022).
chronic heart failure (6 papers, 2015 to 2025). "LA&ALA effectively alleviates symptoms of chronic heart failure and improves ventricular remodeling, a pharmacological effect potentially associated with the AQP1 gene." (PMID 41154077, 2025). "Thus, AQP1 blockers could have clinical potential in the refractory edema that is associated with congestive heart failure and cirrhosis." (PMID 30972964, 2019). "Studies have found that the XinLi Formula alleviates chronic heart failure by regulating the interaction between AGTR1 and AQP1." (PMID 41333015, 2025).
Cirrhosis (6 papers, 2018 to 2025). A chronic disorder of the liver in which liver tissue becomes scarred and is partially replaced by regenerative nodules and fibrotic tissue resulting in loss of liver function. "AQP1 gene-deficient (KO) mice with cirrhosis show decreased angiogenesis, fibrosis, and portal hypertension, which depend on osmotically sensitive microRNAs in the AQP1 pathway." (PMID 39335570, 2024). "Increased expression of AQP1 in peritoneum was also observed in patients with cirrhosis with ascites." (PMID 41034523, 2025). "QSZSP inhibits MAPK activation and AQP1 protein expression in the “liver-peritoneal-kidney” axis to alleviate ascites injury in cirrhosis." (PMID 35399826, 2022). "Importantly, Piezo1 activation in LSECs was induced when exposed to high hydrostatic pressure, which was similar to LSEC/endothelial dysfunction in cirrhosis, and subsequently triggered nuclear translation of NF-κB and stimulated AQP1 expression." (PMID 41034523, 2025). "It was proved that QSZSP can inhibit the activation of MAPK signaling pathway and protect liver function in cirrhotic ascites rats, and it was found that AQP1 of “liver-peritoneal-kidney” axis plays a facilitating role in the process of ascites in cirrhosis ascites." (PMID 35399826, 2022). "First, immunohistochemical staining of AQP1 in LESCs demonstrated AQP1 expression in patients with cirrhosis with ascites was higher than in patients without cirrhosis and patients with cirrhosis without ascites." (PMID 41034523, 2025).
endometrial cancer (6 papers, 2013 to 2026). Primary or metastatic malignant neoplasm involving the endometrium (mucous membrane that lines the endometrial cavity). "The exciting discovery was that the AQP1 ion channel blockers inhibited invasiveness of both low- and high-grade endometrial cancer types in established cell lines and primary cancer cells at doses that did not cause toxic side effects." (PMID 37760476, 2023). "As reported here, drug-like agents that we have found block the ion channel function of a specific membrane protein known as Aquaporin-1 (AQP1) can be used to inhibit invasiveness of endometrial cancer cells." (PMID 37760476, 2023). "AQP1 expression in endometrial cancer has been correlated with histologic grade, extent of myometrial invasion and the likelihood of extrauterine metastasis, but the functional role of AQP1 in this tissue remains to be defined." (PMID 32679804, 2020). "Furthermore, it is known that estrogen induces AQP1 expression by activating the estrogen-response element in the promoter of the Aqp1 gene during angiogenesis in human breast and endometrial carcinomas." (PMID 24252214, 2013). "Combining ion channel inhibitors of AQP1 with hormonal therapy in patients with endometrial cancer could address resistance to hormonal treatments, and could also help reduce the intensity of regular cancer treatments needed, sparing patients from the associated side effects." (PMID 37760476, 2023).
endothelial dysfunction (6 papers, 2018 to 2025). In vascular diseases, endothelial dysfunction is a systemic pathological state of the endothelium (the inner lining of blood vessels) and can be broadly defined as an imbalance between vasodilating and vasoconstricting substances produced by (or acting on) the endothelium. "In this work, we conducted a comparative analysis of AQP1 expression in aortic ECs derived from young and aged mice, revealing an age-associated upregulation of AQP1 concurrent with endothelial dysfunction." (PMID 39180980, 2024). "The positive association between endothelial AQP1 expression with age in mice alongside concurrent endothelial dysfunction, underscores the potential key role of AQP1 in induction of EC senescence and vascular decline in aging." (PMID 39180980, 2024). "It was documented that AQP1 is expressed in human atherosclerotic lesions and its deficiency was related to endothelial dysfunction and atherosclerosis progression." (PMID 29301341, 2018). "A loss of AQP1 is associated with endothelial dysfunction and atherosclerotic progression." (PMID 37143707, 2023). "In conclusion, our results add further support to AQP1 as a candidate player in the setting of endothelial dysfunction and CVD." (PMID 29301341, 2018). "Our results support the involvement of impaired AQP1-mediated water transport in endothelial dysfunction and activation." (PMID 29301341, 2018). "Although further investigation is needed to validate this hypothesis, our results suggest that AQP1 is a candidate player in the setting of endothelial dysfunction." (PMID 29301341, 2018). "The underlying mechanism was not identified; however, AQP1 channels in the endothelial cells could, perhaps, contribute to washing out substances, such as LDL, trapped in the subendothelial intimal layer in areas of endothelial dysfunction." (PMID 35203568, 2022).
heart failure (6 papers, 2021 to 2025). Inability of the heart to pump blood at an adequate rate to meet tissue metabolic requirements. "Our study explores the effects of AQP1 deficiency on physiological parameters such as the baseline rate of heart failure and blood pressure and aims to clarify the relationship between AQP1 deficiency and alterations in the gut microbiota." (PMID 40723374, 2025). "Based on our previous findings regarding the association between the heart failure model and AQP1 knockout, we selected the high-dose treatment group, which exhibited the most pronounced therapeutic effects, for gut microbiota sequencing." (PMID 41154077, 2025). "Collectively, these results demonstrate that AQP1 deficiency leads to marked alterations in gut microbial richness and diversity in the context of heart failure." (PMID 40723374, 2025). "Complementary assessments, including cardiac ultrasound evaluation, blood pressure measurement, and the analysis of 24 h urine volume, were also conducted to gain a comprehensive understanding of the systemic effects of AQP1 deficiency in the context of heart failure." (PMID 40723374, 2025). "Studies in AQP1-KO mice have shown that AQP1 dysfunction is linked to heart failure." (PMID 39768394, 2024). "Human heart failure is associated with a reversible up-regulation of myocardial AR and AQP1." (PMID 34768373, 2021). "This shows that the effect of LA&ALA on heart failure—particularly in reducing NT-ProBNP—is highly dependent on AQP1 expression." (PMID 41154077, 2025). "AQP1 participates in multiple pathological processes in heart failure, including myocardial interstitial edema, inflammation-driven angiogenesis, and tissue repair." (PMID 41154077, 2025). "Aquaporin 1 (AQP1) is widely expressed in myocardial cells and is closely associated with the physiology and pathology of heart failure progression." (PMID 40723374, 2025). "In C57 mice, the expression of AQP1 protein increased with the progression of heart failure (HF), indicating a correlation between AQP1 expression and heart failure." (PMID 41154077, 2025). "Moreover, substantial differences were observed in the intestinal microbiota profiles between AQP1 knockout mice with heart failure and their wild-type counterparts." (PMID 40723374, 2025). "VEGF—a major mediator of angiogenesis and vascular permeability—may be activated via LA&ALA to promote vascular regeneration and alleviate heart failure symptoms, indicating that this pharmacological effect operates through an AQP1-independent pathway." (PMID 41154077, 2025). "Our study, through sequential analysis of endomyocardial biopsies suggests that heart failure, independent of etiology, is associated with overexpression of AR and AQP1." (PMID 34768373, 2021).
Hyperglycemia (6 papers, 2016 to 2023). An increased concentration of glucose in the blood. "As endothelin-1 and fibronectin overproduction and apoptosis are characteristic features in both hyperglycemia and hypoxia, we evaluated the effect of AQP1 overexpression on these phenomena." (PMID 27383386, 2016). "AQP1 overexpression in ECs suppressed hyperglycemia-induced cellular hypoxia, endothelin-1 and fibronectin overproduction, and apoptosis." (PMID 27383386, 2016). "To clear the involvement of AQP1 on hyperglycemia-induced ROS generation, we also investigated the effect of AQP1 overexpression on 8-OHdG formation in BAECs." (PMID 27383386, 2016). "Specifically, in diabetic Ins2Akita mice, retinal COX-2 and AQP1 are upregulated concomitant with increased angiogenesis, suggesting the relevance of our observations in an in vivo setting where hyperglycemia is the main driver of microvascular disease." (PMID 26822858, 2016). "We examined the effect of AQP1 overexpression on hyperglycemia-induced mtROS generation." (PMID 27383386, 2016). "However, it is important to note that AQP1 may serve as a molecular target to prevent diabetic complications because hyperglycemia-induced endothelin-1 and fibronectin overproduction and apoptosis were all suppressed by overexpression of AQP1." (PMID 27383386, 2016).
neuromyelitis optica (6 papers, 2013 to 2024). A rare inflammatory disease of the central nervous system characterized mainly by attacks of uni- or bilateral optic neuritis (ON) and acute myelitis. "Antibodies against AQP4 and AQP1 have been consistently observed in the sera from patients with neuromyelitis optica (NMO)." (PMID 30380700, 2018). "Antibodies against AQP1 (anti-AQP1) and AQP4 (anti-AQP4) have consistently been identified in the sera of patients afflicted with neuromyelitis optica (NMO)." (PMID 39441465, 2024).
triple-negative breast carcinoma (6 papers, 2010 to 2024). An invasive breast carcinoma which is negative for expression of estrogen receptor (ER), progesterone receptor (PR), and human epidermal growth factor receptor 2 (HER2). "High protein expression of AQP1, AQP3 (triple-negative breast cancer) and AQP5 (early and triple-negative breast cancer) revealed a correlation with spread to lymph nodes and poor prognosis." (PMID 37681917, 2023). "In triple-negative breast cancer (TNBC), AQP1 overabundance inhibited RIPK1-mediated necroptosis and promoted progression and metastasis." (PMID 35864548, 2022). "To this end, we used lentiviral infection to express Aqp1 from a strong constitutively active promoter (EF1α) in five cell lines: HT22 (hippocampal), J774A.1 (macrophage), Jurkat (T lymphocyte), MDA-MB-231 (triple-negative breast cancer), and MIN6 (insulinoma)." (PMID 38649904, 2024).
epilepsy (5 papers, 2016 to 2025). A brain disorder characterized by episodes of abnormally increased neuronal discharge resulting in transient episodes of sensory or motor neurological dysfunction, or psychic dysfunction. "Previous studies have reported increased AQP1 expression of astrocytes in surgical samples of the anterior temporal neocortex of patients with drug‐resistant epilepsy." (PMID 38943548, 2024). "Furthermore, alterations in AQP1 would appear to promote glial scar formation, which in turn would produce deleterious effects, including defects in neuronal transmission, alteration of neural network homeostasis, and the onset of drug-resistant epilepsy." (PMID 37569297, 2023).
Hypertension (5 papers, 2018 to 2024). The presence of chronic increased pressure in the systemic arterial system. "AQP1 values in CSF during aging did not vary for the normotensive group, whereas a significant increase in AQP1 levels was observed in the hypertensive rat with increasing untreated hypertension time up to 12 months of age." (PMID 36293145, 2022). "In patients with hypertension, the long-PCR product of AQP1 gene decreased, which showed increased DNA DSBs of the AQP1 gene in proximal tubular cells." (PMID 32099032, 2020). "As a result, the expression of DNA methyltransferases DNMT1, 3 A, and 3B and DNA demethylation enzymes TET1 and 3, after correction for AQP1, increased in patients with hypertension." (PMID 32099032, 2020). "In patients with hypertension, DNA DSBs of the AQP1 gene were increased with elevated urine DNMTs/AQP1 and TETs/AQP1 expression." (PMID 32099032, 2020). "Immunofluorescence was performed in different eye structures to analyze the effects of hypertension in the expression of AQP1, AQP4, and the Na+/K+ ATPase α1 and α2 subunits." (PMID 30428541, 2018). "The present study indicates that, especially in proximal tubular cells that express AQP1, modulation of DNA methylation through DNMTs may be conducted actively in patients with hypertension, although the DNA methylation status itself has not been examined in this study." (PMID 32099032, 2020).
inflammatory bowel disease (5 papers, 2015 to 2023). A spectrum of small and large bowel inflammatory diseases of unknown etiology. "The reduced mRNA expression of several AQPs (AQP1, AQP3, AQP7 and AQP8) in human intestinal mucosa has been demonstrated at the early stage of inflammatory bowel diseases (IBD), including Crohn’s disease and ulcerative colitis." (PMID 27589719, 2016).
kidney cancer (5 papers, 2014 to 2025). Primary or metastatic malignant neoplasm involving the kidney. "Further evaluation of AQP1 as a noninvasive kidney cancer biomarker should include larger cohorts, more quantitative measurements, and statistical analyses of not just clear cell and papillary RCCs but all renal masses, benign and malignant." (PMID 24803718, 2014). "Results of this experiment support the idea that urinary AQP1 is present and elevated in patients with kidney cancer and could therefore be useful in classifying incidentally discovered renal masses." (PMID 24803718, 2014).
myocardial infarction (5 papers, 2015 to 2021). Gross necrosis of the myocardium, as a result of interruption of the blood supply to the area, as in coronary thrombosis. "HIF-1α induced regulation of AQP1 has also been linked to edema in peripheral nerve injury in Schwann cells and after myocardial infarction." (PMID 33644043, 2021). "In a myocardial infarction model, cardiomyocytes deficient in AQP1 showed a reduced level of apoptosis, suggesting AQP1 has a positive role in the execution of the cell death process." (PMID 33324655, 2020). "The aim of this research was to determine both if and how AQP1 is associated with cardiac ischemic injury, particularly the development of edema following myocardial infarction (MI)." (PMID 26348407, 2015). "AQP1 is also involved in angiogenesis in other tissues such as in heart tissue after myocardial infarction, in neovascularization of the cirrhotic liver, and in tube formation of human retinal vascular endothelial cells." (PMID 27252655, 2016). "They found an upregulation of AQP1, 4, and 6 in response to myocardial infarction." (PMID 31027200, 2019). "The results of p-nitro-blue tetrazolium staining were characterized by reduced myocardial infarct size, and a serum analysis of myocardial enzyme levels (data not shown) demonstrated reduced cardiac injury following the ligation of the LAD in the AQP1−/− mice." (PMID 26348407, 2015).
Nephropathy (5 papers, 2017 to 2022). A nonspecific term referring to disease or damage of the kidneys. "In contrast, AQP1 overexpression can alleviate aristolochic acid-induced nephropathy." (PMID 35280255, 2021). "AQP1 and NKCC2 are apically expressed in the proximal tubule and thick ascending limb, respectively, and are increased in various types of nephropathy." (PMID 28246612, 2017). "On the basis of this evidence, in this work, we analyzed the urinary excretion of AQP1, AQP2, and AQP5 in three groups of patients: 12 diabetic with no sign of nephropathy (DM), 12 diabetic with histologic diagnosis of diabetic nephropathy (DN), and 11 diabetic with nondiabetic nephropathy (NDN)." (PMID 28246612, 2017).